IL17C (interleukin 17C)
Diseases named in the same sentence as IL17C in open-access papers (continued):
Sharing a sentence is not in itself a finding about the gene and the disease.
inflammation (5 papers, 2015 to 2023). Aberrant reaction of the microcirculation characterized by movement of fluid and leukocytes from the blood into extravascular tissues. "Since IL-17C and IL-17RE are expressed in the skin and have been shown to be pathogenic in mouse models of dermal inflammation, we hypothesized that the most likely setting in which the IL-17C/IL-17RE axis might participate in antifungal immunity would be in cutaneous C. albicans infections." (PMID 25849644, 2015). "The airways epithelial cells produce proinflammatory cytokines including Il17c along with growth factors, and chemokines that draw inflammatory cells into the airways during lung inflammation." (PMID 30709343, 2019). "Pulmonary inflammation was remarkably reduced in Il-17c-/- mice." (PMID 33411748, 2021).
infectious disease (2 papers, 2020 to 2024). A disorder directly resulting from the presence and activity of a microbial, viral, or parasitic agent in humans. "Activation of TLR is one of the first responses of the immune system after contact with pathogens, which explains the early upregulation of IL17C in the various infectious diseases." (PMID 32174926, 2020). "First, we will take a closer look at the role of the IL-17C/RE immune axis in infectious diseases." (PMID 32174926, 2020).
benign tumors (1 paper, 2018). "Of these, 15 proteins (PRSS8, MK, WFDC2 (HE4), IL-10, SOD2, PARP-1, hK11, PVRL4, MUC-16 (CA125), FR-alpha, CDH3, NTRK3, IL-8, IL-17C, EN-RAGE) were selected from the comparison between OC stage I–IV and benign tumors." (PMID 30519148, 2018).
metabolic disorders (1 paper, 2017). "The use of complementary cross-enrichment analysis tools (Set Distiller and String) can be applied to extract useful functional insights or links of genes such as IL-17C and IL-23A that are important in the pro-inflammatory response of immunity and autoimmune or metabolic disorders." (PMID 28099447, 2017).
IL17C also shares sentences with these, for which no sentence is quoted: ankylosing spondylitis (2 papers); hidradenitis suppurativa (2); psoriatic arthritis (2); Stroke (2); acne (1); acute kidney injury (1); bipolar disorder (1); blepharitis (1); Cardiovascular disease (1); colon cancer (1); contact dermatitis (1); disseminated candidiasis (1); eczema (1); esophageal squamous cell carcinoma (1); folliculitis (1); gastric cancer (1); hepatocellular carcinoma (1); Lewis lung carcinoma (1); lymph node metastasis (1); mucositis (1); multiple sclerosis (1); neurological diseases (1); oral squamous cell carcinoma (1); osteoarthritis (1); rheumatoid arthritis (1); Sepsis (1); systemic inflammatory response syndrome (1); systemic lupus erythematosus (1); systemic sclerosis (1); tenosynovitis (1).
A further 1 disease shares a sentence with IL17C in 1 paper.